CXCR4 (C-X-C motif chemokine receptor 4)
Diseases named in the same sentence as CXCR4 in open-access papers (continued):
Sharing a sentence is not in itself a finding about the gene and the disease.
tumor (3,077 papers, 2002 to 2026). "We identified extensive cellular heterogeneity within the TME, dominated by CMS2/CMS3 epithelial states, SPP1+ tumor-associated macrophages, diverse T-cell subsets, and CXCR4+ B cells." (PMID 41683916, 2026). "Further co-culture experiments revealed that CXCR4 promoted the polarization of tumor-associated macrophages (TAMs) to M2 type through glutamine metabolic reprogramming and induced the exhaustion of CD8+ T cells, thereby intensifying immune escape." (PMID 42082463, 2026). "Brain tissue damage caused by tumor invasion activates neighboring microglia through the CXCR4 signaling axis, further augmenting tumor invasive potential." (PMID 41583906, 2026). "It is involved in physiopathological processes such as growth and development, immunoinflammation, tumor invasion, wound healing, and fibrosis through various pathogenic mechanisms; CXCR4 is a promising therapeutic target." (PMID 40308758, 2025). "An example is that USP1 and USP18 promote M2 polarization and tumour progression by deubiquitinating and stabilizing attractive receptors, including CXCR4 and CSF1R respectively in tumour-associated macrophage." (PMID 41562074, 2025). "It is demonstrated by our study that TGFβ-1 and CXCR4 are critical factors in the tumorigenesis of BC and their inhibition shows interference with tumor-associated pathways in a synergistic way." (PMID 41348904, 2025). "As such, elevated expression of CXCR4 is significantly associated with high-grade and advanced-stage ccRCC, as well as high rates of tumor recurrence." (PMID 39920694, 2025). "In MCF-7 cells, exposure to the hypoxia–mimetic agent cobalt chloride (CoCl2) led to a marked upregulation of CXCR4, a chemokine receptor associated with tumor progression and metastasis." (PMID 40806452, 2025). "CXCL12 expressed by cancer-associated fibroblasts then banded to CXCR4 on tumor cells and induced epithelial-mesenchymal transformation, ultimately promoting metastasis to secondary tumor sites." (PMID 41347146, 2025). "In CRC, elevated expression of CXCR4 in tumor cells is strongly associated with increased metastasis, higher recurrence rates, and reduced overall survival." (PMID 41233827, 2025). "Many studies using clinical samples as well as cell lines implicated CXCR4 as a marker for normal human renal progenitor cells and for the tumor progenitor cells in ccRCC (Studies 2, 3, 7)." (PMID 39920694, 2025). "While prior studies have primarily focused on CXCR4 expression in cancer cells and its role in metastasis, a few have examined its involvement in tumor-associated vasculature." (PMID 41210695, 2025). "This is particularly notable given emerging evidence that tumor-associated macrophages (TAMs) can directly phagocytose viable cancer cells via modulation of the CD47/CXCR4/CXCL12 axis, a process referred to as “immune surrender”." (PMID 40563669, 2025). "The elevated expression of CXCR4 in GBC has been associated with increased tumor aggressiveness and risk of recurrence, as well as a poor prognosis, highlighting its significance in the disease’s progression and its potential as a therapeutic target." (PMID 40142263, 2025). "While both approaches utilize CXCR4 overexpression for tumor targeting, the first emphasizes diagnostic precision and potential for AI-driven image segmentation." (PMID 40806525, 2025). "This further reveals that B cells in the TDLN promote the migration and LN metastasis of tumor cells by producing pathogenic IgG antibodies that activate the CXCR4/SDF1α axis within tumor cells." (PMID 40904508, 2025). "Subsequently, SIRT1 regulates the migration of tumor-associated macrophages (TAMs) through the CXCR4/CXCL12 pathway, which inhibits the proliferation and activity of CD8+ T cells." (PMID 40567502, 2025).
tumor (continued). "The inclusion of CXCR4E was intended to block the suppressive pathway driven by cancer-associated fibroblast secretion of CXCL12, which binds CXCR4 on T cells to hinder their tumor engagement and dampen responsiveness to CXCL10." (PMID 41294574, 2025). "The positive expression of CXCR4/VEGF serves as an indicator of tumor metastasis and progression and is associated with a low survival rate." (PMID 40600065, 2025). "As a response to the changes in the microenvironment caused by obesity, tumor cells adjust the expression of chemokine receptors (such as CXCR4, CXCR7, and CCR2)." (PMID 40076892, 2025). "Several inflammatory mediators, including interleukins (IL-6, IL-8, IL-10), tumor necrosis factor (TNF), and chemokines (CXCL12, CXCR4), are implicated in tumor progression and the pathological inflammatory microenvironment of these tumors." (PMID 40433410, 2025). "Although previous studies have explored CXCR4 expression in cancer cells and its role in promoting metastasis, comparatively few have addressed its function within tumor-associated vasculature, particularly in relation to angiogenesis and vascular remodeling." (PMID 41210695, 2025). "CXCR4, a chemokine receptor highly expressed in various tumor cells, is closely associated with tumor invasion and metastasis." (PMID 39911388, 2025). "CXCR4 expression was found in the cytoplasm and cell membrane, linked with tumour invasion and interaction with CAF." (PMID 41312167, 2025). "The researchers found that evasion of primary tumours and establishment of distant metastasis in Pancreatic ductal adenocarcinoma were caused by pancreatic CSCs, co-expressed with CXCR4 chemokine receptors." (PMID 40852716, 2025). "The activation of the CXCR4/CXCL12 axis was shown to upregulate a series of miRNAs that interact with tumour associated macrophages at the invasive fronts of tumours, resulting in M2 polarisation of these macrophages." (PMID 39982274, 2025). "included 2037 patients, showing that CXCR4 expression correlates with lymph node metastasis, distant metastasis, tumor staging, and survival, with higher expression associated with shorter survival." (PMID 40607416, 2025). "In fact, CAFs are believed to recruit EPCs to BC TME via the secretion of massive amounts of CXCL-12, which interact with CXCR4 on EPCs, promoting tumor angiogenesis after differentiation into tumor-associated vascular endothelial cells (TAVECs)." (PMID 39609700, 2024). "Using the CellChat R package, intercellular communication analysis revealed that tumor-associated macrophages (TAMs) interact with other cells in the PCa TME primarily through MIF - (CD74+CXCR4) and MIF - (CD74+CD44) ligand-receptor pairs." (PMID 38663915, 2024). "For example, NK cells were engineered to overexpress CAR mRNAs encoding activating receptors (CD16 or CXCR4) to enhance their tumor targeting and cytotoxicity, thereby facilitating tumor immunotherapy." (PMID 39310113, 2024). "C-X-C motif chemokine 12 (CXCL12, also known as stromal cell-derived factor 1, SDF-1) and its receptor, C-X-C chemokine receptor type 4 (CXCR4), play an important role in angiogenesis and are associated with tumor progression." (PMID 39201522, 2024). "The presence of tumor-associated lymphatic vessels also promotes the exit of CD8+ T cells via the CXCL12 – CXCR4 chemotaxis, reducing the retention of tumor-specific CD8+ T cells." (PMID 39211044, 2024). "High mRNA expression of CDK1, PCNA, EZH2, BUB1, and CXCR4 in tumor was significantly associated with lower RFS." (PMID 38831458, 2024). "CXCL12 from tumor-associated fibroblasts was found to be able to recruit M2-type macrophages and block CXCR4, the receptor for CXCL12, significantly reducing M2-type macrophage chemotaxis." (PMID 39403370, 2024). "The signaling pathway of SDF-1 and its receptor CXC chemokine 4 (CXCR4) has been implicated in angiogenesis, tumor growth, embryogenesis, and wound healing." (PMID 39125605, 2024).
tumor (continued). "C-X-C chemokine receptor type 4 (CXCR4) is a protein whose high expression in GBM tumours was found to be associated with shorter overall survival (OS)." (PMID 39008219, 2024). "In this framework, the Runt-related transcription factor 2 (RUNX2) and the C-X-C motif chemokine receptor 4 (CXCR4) have emerged as proteins of interest, being associated with the migration, invasion, and metastasis of tumour cells." (PMID 38474372, 2024). "Collectively, these data suggest that delayed neutrophil apoptosis induced by tumor‐derived G‐CSF/GM‐CSF is associated with an increased percentage of viable CXCR4+ neutrophils in vitro." (PMID 39447112, 2024). "Highly selective, small molecule CXCR4 antagonist was reported to suppress tumor growth, prevent distant metastasis and tumor-associated macrophage infiltration in HCC." (PMID 37142825, 2024). "Subsequently, mice with colitis-associated tumorigenesis that were injected with these CXCR4-overexpressing MSCs displayed a reduced tumour burden compared to mice treated with unmodified counterparts." (PMID 39062449, 2024). "Blocking CXCR4 can alter tumor-environment interactions, increase cancer cell susceptibility to drugs, and reduce tumor growth and migration." (PMID 39350256, 2024). "One possible mechanism for this refractory disease lies in the coordinated interplay between tumor cells and cancer-associated fibroblasts (CAFs), including that through the C-X-C chemokine receptor type 4/C-X-C motif chemokine 12 (CXCR4/CXCL12) signaling." (PMID 38587644, 2024). "Immunohistochemical analyses reveal that high levels of CXCL12/CXCR4 are associated with increased tumor aggressiveness and metastatic potential." (PMID 39682247, 2024). "used mouse models of breast cancer to show that treatment with cyclophosphamide causes an increase in CXCR4-expressing perivascular macrophages, which promote tumor revascularization and regrowth via VEGFA signaling." (PMID 39555068, 2024). "The aim of this study was to evaluate the association between CXCR4 expression in tumor tissue and survival in STSs patients treated with neoadjuvant therapy." (PMID 38893721, 2024). "CXCR4 encodes a chemokine receptor whose expression is associated with the formation of lymphoid follicles that we detected outside of the tumor." (PMID 39548591, 2024). "CXCR4 is highly expressed in tumour cells and tumour-associated fibroblasts (TAF) of various cancers." (PMID 37162544, 2023). "Due to the unbalanced nature of the underlying dataset—only a minority of tumor samples strongly expressed CXCR4—we performed an internal validation step." (PMID 36672341, 2023). "Senescent tumor cells induce CXCR4 loss in T cells, which leads to impaired leukocyte migration and the inhibition of CD8+ T-cell infiltration." (PMID 37372958, 2023). "As for the biomarker, chemokine CXCR4 plays an essential role in tumor dissemination and progression, and is associated with inferior outcome." (PMID 38030989, 2023). "CXCR4 encodes a chemokine receptor and has been reported to be a prognostic biomarker associated with the tumour immune microenvironment in GC." (PMID 37118990, 2023). "The CXCL12 that is released from tumor cells or at the site of tissue damage can interact with CXCR4 on the mesenchymal stem cell membrane (MSCM) to cause MSCs to accumulate at tumor sites." (PMID 36756155, 2023). "The aim of the present study was the evaluation of the differential CXCR4 expression in RCC primary tumor and metastatic tissue as well as in variant renal histologies." (PMID 36982302, 2023). "CXCL12 is a cancer-associated fibroblast derived factor which recruit CXCR4-expressing monocytes toTME and skew to M2-like macrophages to promote tumor growth." (PMID 36816959, 2023). "DNA hypomethylation in the CXCR4 gene has been observed in breast cancer, colorectal cancer, pancreatic cancer and melanoma, and this is associated with tumor progression." (PMID 37190171, 2023).
tumor (continued). "Analyzing exclusively the stroma of tumor samples, the CXCR4 expression was associated with tumor differentiation, P-value = 0.05." (PMID 37697316, 2023). "On the other hand, CXCL12 is produced by several solid tumors and tumor-associated MCs express CXCR4." (PMID 37047288, 2023). "The PTEN loss in PC cells is associated with enhanced expression of CXCL12 and CXCR4 expression and contributes to tumor growth and metastasis." (PMID 38239314, 2023). "Taken together, our results suggest the underlying mechanism of targeting CXCR4 with AMD3100 to inhibit trastuzumab-resistant tumor cell growth operates via mitotic catastrophe and mitotic death." (PMID 37280713, 2023). "The CXCR4 is recognised for its elevated expression in CSCs across more than 20 human tumour types, and it is associated with tumorigenicity, angiogenesis, invasion, and resistance to chemotherapy." (PMID 38139085, 2023). "Tumor stage, invasion depth, lymph node metastases, vascular invasion, and poor prognosis were strongly linked with CXCR4 expression in patients with GC." (PMID 37629071, 2023). "Other previous studies have indicated that the over‐expression of CXCR4 is associated with lymph node metastasis, ulceration, tumour thickness, the stage the tumour is in and overall survival." (PMID 37170733, 2023). "In the current study, we demonstrated that the increased CXCR4 expression in trastuzumab-resistant tumor cells is associated with cell cycle progression and reaches a peak in the G2/M phases, contributing to cell proliferation and survival." (PMID 37280713, 2023). "The up-regulation of CXCR4 has been linked to tumour development, angiogenesis, invasion and migration." (PMID 37162544, 2023). "Some studies have shown that Rh-endostatin can reduce the increased CXCR4 expression involved in the recruitment of Tumor-associated macrophage due to radiotherapy, promote the normalization of tumor blood vessels, and thus enhance the radiotherapy effect." (PMID 38115908, 2023). "The main tumor clone of this patient (56.8% of cells) presented a CXCR4 mutation and was homozygous for MYD88L265P, possibly due to an acquired uniparental disomy (aUPD) of chromosome 3 (chr3)." (PMID 37493341, 2023). "Among the genes examined, we were very interested in the expression of CXCR4, as CXCR4 is reportedly associated with tumor growth, and some studies indicated that CXCR4 affects the proliferation and activity of Tregs in the tumor microenvironment." (PMID 35358193, 2022). "During the current study, we also found mutations of Smarca4, Runx3 and Cxcr4 in early disseminated tumor cells." (PMID 36424557, 2022). "During the evolution of tumor cells, driver mutation occurred in a large number of oncogenic genes, including Smarca4, Cxcr4, Ctnnd2 and Ank1." (PMID 36424557, 2022). "Multiple molecules implicated in the radiated tumor bed effect or enhanced tumor growth after radiation, such as CXCR4, TGF-beta, IL-1, are members of the SASP." (PMID 35158337, 2022). "Other key PGR-regulated genes were associated with the invasion of cells such as Cxcr4 and Cldn1, two membrane-localized proteins involved in tumor cell invasion and migration." (PMID 35563869, 2022). "It has been observed that neutrophils simultaneously expressing both CXCR2 and CXCR4 in the TME are associated with a N2-like tumor-promoting state." (PMID 36347862, 2022). "As one example, the receptor CXCR4 has previously been implicated for its diagnostic value as its expression on both tumor cells and immune cells was correlated with disease progression." (PMID 35565378, 2022). "The relation among the evaluated markers and clinic pathologic characteristics revealed that CXCR4-positive tumor and CXCR4-positive tumor-infiltrating inflammatory cells were associated with vascular invasion (p = 0.0421 and 0.045) as expected." (PMID 36359736, 2022).
tumor (continued). "While CXCL12 is mainly secreted by cells associated with the tumor microenvironment, CXCR4 is expressed by ECs, cancer cells and cancer stem cells." (PMID 35155581, 2022). "CXCR4 promotes tumour growth, metastasis, angiogenesis and tumour–cell interaction, and its expression is associated with more aggressive tumour behaviour and poorer prognosis." (PMID 36140541, 2022). "Increased CXCR4 expression in the hypoxic conditions of CRC is associated with tumor relapse, liver metastasis, and poor prognosis." (PMID 35791509, 2022). "In the TCGA cohort, density of CD8+ tumor-infiltrating T-lymphocytes showed a strong correlation with CXCR4 expression, underlining that CXCR4 acts as a potent driver of T-cell migration, similar to a recent study." (PMID 36419107, 2022). "The CXCR4 expression was reported to be associated with poor prognosis, and the inhibition of CXCR4 renders tumor cells more sensitive to chemotherapy." (PMID 35774848, 2022). "CXCR4 overexpression in cancer cells is associated with tumour growth, angiogenesis, and metastasis." (PMID 35045088, 2022). "Nine out of 23 studies including 1049 patients examined the association between CXCR4 expression and tumor category." (PMID 35729596, 2022). "It was also reported that elevated expression levels of CXCL12/SDF-1 chemokine and its receptor CXCR4 were associated with increased tumour growth and spread." (PMID 36510219, 2022). "Subsequently, we created the Kaplan Meier survival curve using the association between the absolute CXCR4 expression by tumor cells and RFS." (PMID 35397601, 2022). "The increment of the chemokine receptor CXCR4 on the NB cell surface has been associated with aggressive tumor behavior such as cell proliferation, migration, and invasion." (PMID 35715791, 2022). "The results indicated that elevated CXCR4 expression in the group of membrane and/or cytoplasm group and the cytoplasm group was significantly associated with advanced tumor stages and TNM stages." (PMID 35729596, 2022). "Multivariate analysis indicated that CXCR4 expression was positively associated with tumor size, clinical stage, and histological grade of BC." (PMID 36103228, 2022). "CXCR4 has been implicated in the migration of 4T1 tumor cells, resulting in systemic metastasis to lymph nodes through chemotactic signaling from ligands expressed by LECs." (PMID 35740673, 2022). "Another striking difference between the Dx and Re is that genes associated with the tumor microenvironment, the interaction between stroma cells and leukemic blasts (CXCR4 and CXCL8) were lower expressed in cluster 5 (Re) compared to cluster 4 (Dx)." (PMID 35986270, 2022). "The MIF/CXCR4 axis has been described in different cancer types as a critical autocrine pathway linked to tumor progression." (PMID 35715791, 2022). "The results showed that elevated CXCR4 expression was associated with advanced tumor stages (OR 2.95, 95% CI 1.37–6.34, P = 0.006, I2 = 64.1%) and distant metastasis (OR 5.33, 95% CI 1.68–16.94, P = 0.005, I2 = 82.1%) in the Asian group." (PMID 35729596, 2022). "Overall, the findings reported here highlight the multiple functions of CXCR4 in tumor environments and support the association of CXCR4 overexpression with poor clinical data and a dismal prognosis in a variety of malignancies." (PMID 36293358, 2022). "The, CXCL12 expressed by cancer-associated fibroblasts binds to CXCR4 on tumor cells and induces EMT, which ultimately promotes metastasis." (PMID 35406450, 2022). "In PC, it has been shown that the secretion of SDF-1, the agonist of CXCR4, from cancer associated fibroblasts aids in the recruitment of pro-tumorigenic myeloid cells to the primary tumor site." (PMID 35259193, 2022). "BTKi modulate the TME and tumor B-cell interaction, leading to a redistribution of lymphocytosis caused by inhibition of signaling and function of chemokine receptors (CXCR4, CXCR5) and adhesion molecules." (PMID 35804999, 2022).